SKP2 (S-phase kinase associated protein 2)
Diseases named in the same sentence as SKP2 in open-access papers (continued):
Sharing a sentence is not in itself a finding about the gene and the disease.
melanoma (continued). "Silencing of Skp2 resulted in inhibition of melanoma tumor growth in vitro and in vivo." (PMID 29423113, 2018). "This appears to support the hypothesis that B-RAF and cyclin D1 control expression of Cks1 and Skp2, which, in turn, mediate degradation of p27 in melanoma cells." (PMID 29423113, 2018). "To investigate the role of Skp2 in melanoma development, we constructed tissue microarrays and examined Skp2 expression in melanocytic lesions at different stages, including 30 normal nevi, 61 dysplastic nevi, 290 primary melanomas and 146 metastatic melanomas." (PMID 21386910, 2011). "Cytoplasmic but not nuclear Skp2 expression was associated with five-year overall and disease-specific survival in primary melanoma patients." (PMID 21386910, 2011). "Our data indicate that cytoplasmic Skp2 may serve as a potential biomarker for melanoma progression and a therapeutic target for this disease." (PMID 21386910, 2011). "Cytoplasmic Skp2 staining and clinicopathological characteristics of melanomas." (PMID 21386910, 2011). "Due to loss of biopsy cores or insufficient tumor cells present in the cores, 30 normal nevi, 61 dysplastic nevi, 290 primary melanomas and 146 metastatic melanomas could be evaluated for Skp2 staining and included in the present study." (PMID 21386910, 2011). "In melanoma, Skp2 plays a key role in promoting cell cycle progression." (PMID 21386910, 2011). "Increased cytoplasmic Skp2 expression was associated with a poor five-year disease-specific survival of patients with primary melanoma (P = 0.018) but not metastatic melanoma (P>0.05)." (PMID 21386910, 2011). "Our results showed that miR-590-5p could inhibit melanoma cell development by targeting Skp2." (PMID 35845132, 2022). "We further compared mucosal melanoma from patients of European and Asian ancestry (n = 48 and 42) and found that SF3B1 mutations were predominately observed in the former (22.9% vs. 2.4%), while SKP2 amplifications were more frequent in the latter (4.2% vs. 19%)." (PMID 35706047, 2022). "We hypothesized that the role of Skp2 in melanoma cells may be regulated by miR-590-5p." (PMID 35845132, 2022). "Furthermore, Skp2 knockdown inhibits melanoma growth, suggesting that dysregulation of p27 may be a critical step in melanoma tumorigenesis." (PMID 25593992, 2014). "Our study showed that cytoplasmic Skp2 expression was gradually increased from normal nevi, dysplastic nevi to melanoma tissues, indicating that increased cytoplasmic Skp2 expression may be involved in the development of dysplastic nevi and melanoma." (PMID 21386910, 2011). "Targeting Skp2, combined use of Skp2 inhibitor and Skp2 degradation promoting drugs, was proved to be a solution to BRAF inhibitor resistance melanoma." (PMID 37089937, 2023). "In summary, our meta-analyses of 147 acral and 93 mucosal melanomas identified PTPRJ, FER, SKP2, LZTR1, CIC, and PRKN as part of a long tail of driver events that deserves further study and characterization." (PMID 35706047, 2022). "In our study using melanoma cell lines, PCTAIRE1 knockdown up-regulates p27 expression, indicating that, similarly to Skp2, PCTAIRE1 plays an important role in p27 dysregulation." (PMID 25593992, 2014). "Immunohistochemical expressions of 12 promising biomarkers (pAkt, Bim, BRG1, BRMS1, CTHRC1, Cul1, ING4, MCL1, NQO1, SKP2, SNF5 and SOX4) were studied in 122 melanomas and 33 dysplastic nevi on tissue microarrays." (PMID 23028750, 2012). "The Skp2 staining was found consistent when two different antibodies were used in a small TMA including 20 cases of nevi and 20 case of melanomas." (PMID 21386910, 2011). "Thus, targeting Skp2 in gene therapy may hold promise for melanoma treatment." (PMID 21386910, 2011). "In melanoma cells, the efficacy of MLN4924 has been correlated with the ability of preventing the degradation of p21WAF1, a known substrate of SKP2, providing an indirect demonstration of a link between the levels of SKP2 and the efficacy of MLN4924." (PMID 35197103, 2022).
melanoma (continued). "Skp2 was highly expressed in both malignant melanoma cells and tissues, as opposed to normal tissue cells." (PMID 35845132, 2022). "In our studies, FKA downregulated the protein expression of Skp2 in all tested cancer cell lines that were derived from prostate, breast, renal, liver, lung, colon, and cervical cancers, melanoma and osteosarcoma, regardless of their genetic background." (PMID 28335434, 2017). "In melanoma cell lines, the expression of Skp2 is significantly increased and in a negative correlation with p27Kip1." (PMID 28544818, 2017). "This is also in accordance with literature reports of negative or weak expression of Skp2 protein in benign cutaneous melanocytic lesions and high levels in melanomas." (PMID 23385514, 2013). "Thus, increased cytoplasmic Skp2 expression contributes to melanoma invasion possibly through multiple pathways since both Akt and MMP proteins play import roles in melanoma invasion and metastases." (PMID 21386910, 2011). "Cytoplasmic but not nuclear Skp2 expression was gradually increased from normal nevi, dysplastic nevi, primary melanomas to metastatic melanomas." (PMID 21386910, 2011). "Mechanistic studies have shown that Skp2 inhibition of BRAFV600E is dependent on c-Myc transcription factors by specifically binding to the E-box region on the Skp2 promoter, suggesting that targeting Skp2 might be a promising treatment in BRAF inhibitor resistant melanomas." (PMID 34068643, 2021). "However, they found that the nuclear but not the cytoplasmic Skp2 expression correlated with a reduced survival time in melanoma." (PMID 21386910, 2011). "As SKP2 reduction was observed after PSMD14 knockdown (data not shown), the inhibition of proteasome activity by PSMD14 knockdown and the inhibition of p27 degradation through SKP2 reduction may cause the accumulation of p27 protein in melanoma." (PMID 33154524, 2020).
colorectal cancer (34 papers, 2008 to 2025). A primary or metastatic malignant neoplasm that affects the colon or rectum. "In the present study, we found that the depletion of Skp2 (S-phase kinase-associated protein 2) enhances irradiation-induced apoptosis, accompanied by the decrease of the Mcl-1 protein level in human colorectal cancer cells." (PMID 35301297, 2022). "Correspondingly, SKP2 degradation has been reported to suppress aerobic glycolysis and inhibit colorectal cancer growth, underscoring its role in promoting glycolytic metabolism and tumor progression." (PMID 41241099, 2025). "The protein Skp2 is overexpressed in colorectal cancers and is important for glycolysis to take place." (PMID 37568716, 2023). "Dioscin markedly reduced glycolysis by attenuating phosphorylated Skp2 levels in the colorectal cancer cell lines." (PMID 37568716, 2023). "Another natural plant‐derived steroid saponin, dioscin, has been shown to promote CDH1‐mediated polyubiquitination and degradation of SKP2 and a significant reduction in the cell growth of colorectal cancer." (PMID 36881608, 2023). "Menin is an epigenetic calcium-sensing regulator of Skp2 in colorectal cancer (CRC) that binds the SKP2 promoter." (PMID 37089937, 2023). "The oncogenic role of SKP2 reconciles with its overexpression in various human cancers including ovarian adenocarcinoma, breast cancer, lung cancer, colorectal cancer, prostate cancer, leukaemia and squamous cell carcinoma." (PMID 36881608, 2023). "Another study determined that miR-200b/c targeted RECK and subsequently upregulated Skp2 expression and inhibited p27 levels in colorectal cancer cells, resulting in enhanced cell proliferation." (PMID 33621206, 2021). "SKP2 deficiency induces cellular senescence in contexts of oncogenic insults, and recently JARID1B is associated with cellular senescence in colorectal cancer and retinoblastoma cells." (PMID 25596733, 2015). "The ubiquitin ligases CBL and SKP2 were identified as candidate oncogenes, while the ubiquitin ligase FBXW7 is a bona fide tumor suppressor that is mutated frequently in breast and colorectal cancers." (PMID 24874471, 2014). "In colorectal carcinoma, concentrations of Cdh1 and p27 are very low when compared to healthy surrounding tissue, while the expression of Skp2 is inversely higher." (PMID 25000203, 2014). "SKP2 promotes the degradation of phosphorylated cyclin-dependent kinase inhibitor p27 Kip1, and SKP2 overexpression has been shown to contribute to p27Kip1 degradation in lymphomas, colorectal cancer, and GIST." (PMID 23690967, 2013). "High levels of Skp2 have also been shown in a variety of cancers such as prostate, oral squamous carcinoma and colorectal carcinomas." (PMID 23385514, 2013). "Our previous study also showed that Skp2 stabilizes Mcl-1 and thus confers radioresistance to colorectal cancer, suggesting that targeting Mcl-1 could be an extremely promising strategy for cancer treatment." (PMID 37259388, 2023). "Skp2 is frequently overexpressed in various human cancer, including colorectal cancer." (PMID 35301297, 2022). "SKP2 may be a promising therapeutic target for colorectal cancer, and development of SKP2 inhibitors would have a great impact on colorectal cancer therapy." (PMID 32856866, 2020). "Recently, dioscin was identified as a promising inhibitor of Skp2 in colorectal cancer." (PMID 32626765, 2020). "Interestingly, we did observe SKP2 downregulation with paralleled p27KIP1 upregulation in colorectal cancer cells exposed to obatoclax." (PMID 28035994, 2016). "The controversy about Skp2 expression and tumor progression also exists in colorectal carcinoma." (PMID 22533738, 2012). "Additionally, some scholars have found that knocking out S-phase kinase-associated protein 2 (Skp2) could inhibit HK2 expression and glycolysis, and thereby limit the growth of colorectal cancer cells in vivo and in vitro." (PMID 39991762, 2025).
colorectal cancer (continued). "In 5 independent gastric and colorectal cancer cohorts obtained from GEO and TCGA, RNF112 was negatively correlated with FOXM1 downstream genes, including CKS1, CCNB1, SKP2, and FN1." (PMID 37288663, 2023).
gastric cancer (28 papers, 2011 to 2026). A primary or metastatic malignant neoplasm involving the stomach. "Previous studies have shown that HSP70s promote the progression of gastric cancer by stabilizing S phase kinase-associated protein 2 (SKP2)." (PMID 38062023, 2023). "It has been found that rottlerin suppressed cell growth, induced autophagy as well as apoptosis, and reduced migration in addition to invasion in SGC-7901 and MGC-803 GC gastric cancer cells through mTOR and S-phase kinase-associated protein 2 downregulation." (PMID 34572730, 2021). "Skp2, a known oncogene in gastric cancer, thus acts in concert with Gal-3 to repress senescence and promote tumorigenesis." (PMID 40710343, 2025). "Further studies have found that HSP70 inhibition promotes the degradation of SKP2, which affects the cell cycle and promotes apoptosis of gastric cancer cells." (PMID 38698431, 2024). "The results of our study showed that the oncogenic ability of cell proliferation and cancer promotion, represented by SKP2 expression in gastric cancer tissues, was repressed by the expression of Beclin-1 and FOXP3 and thus responded to the survival outcome." (PMID 34414959, 2021). "The SGC-7901, a gastric cancer cell with high Skp2 expression, was selected for the subsequent verification experiment." (PMID 34702937, 2021). "One group reported that miR-508-5p retarded metastasis by inhibition of Skp2 in gastric cancer cells." (PMID 33621206, 2021). "Previous report found that downregulation of Skp2 inhibits the viability, proliferation, colony formation, migration, and invasion and induces apoptosis of human gastric cancer cells." (PMID 29850565, 2018). "When IGF-1 activate mTORC1 pathway in BGC-823 gastric cancer cells, endogenous Skp2 was phosphorylated at Ser64." (PMID 28446188, 2017). "The analysis of 98 patients with gastric carcinoma showed that tumors have a high expression of Skp2, which is inversely correlated to p27 levels." (PMID 25000203, 2014). "Collectively, these findings highlight Gal-3 as a central orchestrator of senescence escape in gastric cancer cells, enabling sustained proliferation through hTERT stabilization, Rb pathway modulation, and regulation of key cell cycle mediators such as Skp2 and p27KIP1." (PMID 40710343, 2025). "EBNA3C may also function in gastric cancer as a transcriptional regulator by interacting with several well-known cellular and viral TFs, and recruits SKP2 to facilitate the degradation of p27KIP1 and pRb." (PMID 39228892, 2024). "We investigated SKP2 expression in human gastric carcinomas." (PMID 34414959, 2021). "Furthermore, both upregulated Skp2 and downregulated p27 were identified to be correlated with poor prognosis in gastric carcinoma and neuroblastoma patients." (PMID 34572430, 2021). "Both mTOR and Skp2 play critical roles in gastric cancer (GC) tumorigenesis." (PMID 28446188, 2017). "To investigate whether mTOR signaling regulate Skp2 expression in gastric cancer, we detected the expression of mTOR and Skp2 in cell lines." (PMID 28446188, 2017). "mTORC1 may function to regulate Skp2 by serving as a priming kinase, which stablizes Skp2 and consequently leads to its oncogenic effects on gastric cancer tumorigenesis." (PMID 28446188, 2017). "Furthermore, we found that NKX6.3 functions as a negative transcriptional regulator of RhoA, Cdc42, Rac1, Rac2, Skp2 and c-Myc genes and completely inhibits c-Myc-p300/CBP-Skp2-Miz1 and Max complex formation, thereby preventing gastric cancer cell migration and invasion." (PMID 27333045, 2016). "However, in gastric cancer, in cells such as AGS, MKN7 and NUGC-3, CLDN6 silencing contributes to cell cycle arrest at the G1-S checkpoint through increasing p21WAF1/Cip1 and p27Kip1 and decreasing S-phase kinase-associated protein 2 (SKP2) protein levels, which are well-known cell cycle regulators." (PMID 36362009, 2022).
gastric cancer (continued). "It has been reported that E2F4 binds directly with USP2 (ubiquitin specific peptidase 2) in gastric cancer cells, while USP2 could bind with SKP2 and USP2-stabilized SKP2 did not destabilize its substrate P21." (PMID 38980592, 2025).
osteosarcoma (25 papers, 2009 to 2026). A usually aggressive malignant bone-forming mesenchymal neoplasm, predominantly affecting adolescents and young adults. "In osteosarcoma studies, silencing of gli2 is found to cause upregulation of p21, inhibition of cyclin D1, SKP2, and phosphorylated Rb, thus inducing G1 phase arrest and ultimately preventing the growth of osteosarcoma." (PMID 37868974, 2023). "Conversely, expression of the Cx43 C-terminal in U2OS (an osteosarcoma cell line) and HeLa cells were found to decrease their rate of cell division, potentially via its interaction with S-phase kinase-associated protein 2 (Skp2)." (PMID 37892142, 2023). "S-phase kinase-associated protein 2 (Skp2) performs oncogenic functions in cancers; however, how Skp2 is regulated post-transcriptionally is elusive in osteosarcoma." (PMID 33621206, 2021). "Another targetable element that could be used in treating resistance due to stem cell properties in osteosarcoma is S-phase kinase-associated protein 2 (Skp2)." (PMID 32961800, 2020). "Similarly, in osteosarcoma, Cx43 CT inhibited cell proliferation by downregulation of S phase kinase-associated protein 2 (skp2) expression, an important component of the Skp1-Cullin-F-box protein (SCF) ubiquitin–ligase complex implicated in p27 ubiquitin–proteasome degradation." (PMID 39936974, 2025). "Knockout (KO) of Skp2 in an immunocompetent transgenic mouse model of osteosarcoma improved survival, drove apoptosis, and induced antitumor immunity." (PMID 41877584, 2026). "Studies have shown that suppression of Skp2 attenuates cell proliferation and invasion in osteosarcoma, while overexpression of Skp2 enhances cell growth and motility." (PMID 39324133, 2024). "Among these hub genes, Skp2 has been reported as an E3 ubiquitin ligase involved in osteosarcoma progression." (PMID 39324133, 2024). "Targeting Skp2 inhibition has demonstrated anticancer effects, leading to survival benefits in osteosarcoma." (PMID 39324133, 2024). "As far as tumor metastasis and senescence is concerned, dysregulation of Skp2 level reduces osteosarcoma cell invasion and lung metastasis both in vitro and vivo." (PMID 37089937, 2023). "A study investigating if inhibiting the Notch pathway prevents osteosarcoma growth demonstrated that a γ-secretase inhibitor attenuated the cyclin D1, cyclin E1, E2, and SKP2 expression." (PMID 36012128, 2022). "We observed that Skp2 cDNA plasmid transfection promoted the expression of Skp2 in osteosarcoma cells." (PMID 33621206, 2021). "We clarified that miR-506 performed anticancer activity via suppression of Skp2 in osteosarcoma cells." (PMID 33621206, 2021). "Our MTT assay results demonstrated that Skp2 downregulation attenuated the viability of osteosarcoma cells and enhanced miR-506-induced inhibition of cell viability." (PMID 33621206, 2021). "The viability of osteosarcoma cells after Skp2 plasmid and miR-506 mimic transfections was evaluated by MTT assay." (PMID 33621206, 2021). "Skp2 upregulation inhibited apoptosis, while miR-506 mimics triggered apoptosis in osteosarcoma cells." (PMID 33621206, 2021). "For example, saurolactam, a natural agent from Saururus chinensis, suppressed proliferation and motility in osteosarcoma cells in part by targeting Skp2, indicating that Skp2 is involved in osteosarcoma progression." (PMID 33621206, 2021). "We found that Skp2 upregulation increased cell migration, while miR-506 overexpression retarded the migratory activity in osteosarcoma cells." (PMID 33621206, 2021).